IP6K3 (inositol hexakisphosphate kinase 3)
Description:
Kinase that converts inositol hexakisphosphate (InsP6) to diphosphoinositol pentakisphosphate (InsP7/PP-InsP5). Regulates cellular phosphate export by binding to the SPX domain of the XPR1 phosphate transporter.
Synonyms: IHPK3; INSP6K3
Tractability: Small molecule: a high-quality ligand is known. PROTAC: ubiquitination databases record sites on it; a small molecule that binds it is known.
Target class: Enzyme; Transferase
Gene: Protein-coding gene on chromosome 6 (33,721,315 to 33,750,520, reverse strand). Ensembl gene ENSG00000161896.
Subcellular location: Cytoplasm
Subcellular location (Human Protein Atlas): Nucleoplasm; Cytosol
Pathways (Reactome):
Metabolism: Synthesis of pyrophosphates in the cytosol
Gene Ontology:
Molecular function: inositol hexakisphosphate 6-kinase activity; inositol hexakisphosphate kinase activity; protein binding; diphosphoinositol pentakisphosphate kinase activity; diphosphoinositol tetrakisphosphate kinase activity; inositol 5-diphosphate pentakisphosphate 5-kinase activity; inositol-1,3,4,5,6-pentakisphosphate kinase activity; inositol hexakisphosphate 5-kinase activity; kinase activity
Biological process: inositol phosphate biosynthetic process; phosphatidylinositol metabolic process; protein phosphorylation; inositol phosphate metabolic process; phosphatidylinositol phosphate biosynthetic process; organophosphate biosynthetic process
Cellular component: cytoplasm; cytosol; nucleus
Genetic constraint (gnomAD): Loss-of-function variants: 20 observed, 28.28 expected, observed/expected ratio (o/e) 0.71, 90% interval 0.5 to 1.03. The upper end of that interval is the gene's LOEUF score, 1.03, which puts it in group 4 of 6, group 1 being the genes least tolerant of losing a copy. Missense variants: 473 observed, 537.78 expected, observed/expected ratio (o/e) 0.88, 90% interval 0.81 to 0.95. Synonymous variants: 207 observed, 224.45 expected, observed/expected ratio (o/e) 0.92, 90% interval 0.82 to 1.03.
Homologues: Orthologues: chimpanzee IP6K3 (99% identical), macaque IP6K3 (95% identical), dog IP6K3 (83% identical), guinea pig IP6K3 (77% identical), rabbit IP6K3 (75% identical), rat Ip6k3 (74% identical), mouse Ip6k3 (74% identical), pig IP6K3 (62% identical), Drosophila melanogaster Ip6k (33% identical), Caenorhabditis elegans F30A10.3 (28% identical), Caenorhabditis elegans lfe-2 (17% identical), Drosophila melanogaster IP3K1 (15% identical). Paralogues in human: IP6K1 (51% identical), IP6K2 (44% identical), ITPKB (19% identical), IPMK (18% identical), ITPKC (18% identical), ITPKA (16% identical).
Diseases named in the same sentence as IP6K3 in open-access papers:
IP6K3 is named in the same sentence as 16 diseases in open-access papers, as found by Europe PMC text mining. Sharing a sentence is not in itself a finding about the gene and the disease. The quoted sentences say what the papers report.
Obesity (3 papers, 2019 to 2022). Accumulation of substantial excess body fat. "In addition to IP6K1, IP6K3 was also associated with obesity and insulin resistance regulation." (PMID 33139672, 2020). "IP6K3 knockout mice showed decreased body weight, fat mass, blood glucose, blood insulin, plasma lactate, and increased glucose tolerance from age induced obesity." (PMID 33139672, 2020). "However, the Ip6k3−/− mouse is not resistant to obesity, and serum insulin and glucose levels of Ip6k2−/− mice are normal." (PMID 31186349, 2019).
Insulin resistance (2 papers, 2020 to 2022). Increased resistance towards insulin, that is, diminished effectiveness of insulin in reducing blood glucose levels. "Ip6k3 expression is limited to skeletal muscle and heart, and its whole-body deletion improves skeletal muscle metabolism, protecting mice from age-induced fat gain, insulin resistance and mortality." (PMID 35216174, 2022). "Genetic deletion of Ip6k3 protects mice from age induced fat accumulation and insulin resistance." (PMID 32204420, 2020). "Ip6k3-KO mice are protected from age induced weight gain and insulin resistance." (PMID 32204420, 2020).
Alzheimer disease (1 paper, 2019). A progressive, neurodegenerative disease characterized by loss of function and death of nerve cells in several areas of the brain leading to loss of cognitive function such as memory and language. "Furthermore, we associated two SNPs in the 5′-flanking promoter region of the IP6K3 gene with the susceptibility to late onset Alzheimer’s disease (LOAD)." (PMID 30744060, 2019).
chronic lymphocytic leukemia (1 paper, 2018). "Several top SNPs (FDR < 0.05) also map to the region adjacent to the classical HLA class II region (e.g., IP6K3 (associated with educational attainment and phosphorus levels) and BAK1 (associated with platelet count, chronic lymphocytic leukemia, and testicular germ cell tumor))." (PMID 29309429, 2018).
diabetes (1 paper, 2016). "We investigated Ip6k3 expression changes in food and muscle-related disease conditions such as diabetes and muscle-disuse atrophy." (PMID 27577108, 2016). "Muscle Ip6k3 expression was induced by diabetes, fasting, and disuse muscle conditions in mice." (PMID 27577108, 2016). "Furthermore, the development of a selective inhibitor of IP6K3 might represent a new class of drug to treat diabetes, which might also have the enticing added benefit of potentially extending lifespan." (PMID 27577108, 2016).
hepatocellular carcinoma (1 paper, 2020). A malignant tumor that arises from hepatocytes. "Ip6k3 is upregulated in NAFLD patients, whereas Ip6k1 and Ip6k2 expression directly correlate with hepatocellular carcinoma (HCC)." (PMID 32204420, 2020).
non-alcoholic fatty liver (1 paper, 2020). A benign form of fatty non-alcoholic fatty liver disease where the disease has not yet progressed to the inflammation of liver. "Genetic deletion of Ip6k1 or Ip6k3 or pharmacologic disruption of IP6Ks protects mice from metabolic diseases including obesity, type-2 diabetes (T2D), non-alcoholic fatty liver (NAFL), osteoporosis, myocardial infarction, ischemia reperfusion injury and aging." (PMID 32204420, 2020).
rhabdomyosarcoma (1 paper, 2016). A rare aggressive malignant mesenchymal neoplasm arising from skeletal muscle. "Similar images were obtained from the human SJCRH30 rhabdomyosarcoma cell line, which expresses detectable IP6K3 mRNA baseline levels." (PMID 27577108, 2016).
tumor (3 papers, 2014 to 2016). "Of these up-regulated genes, the greatest impact was on the expression of CIDEA (14.0-fold increase, p<0.0067), GML (26.4-fold increase, p<0.0004), and IP6K3 (18.1-fold increase, p<0.0001) in the LS-174T tumor xenografts." (PMID 25268703, 2014). "Out of these genes, 1 gene (Ip6k3) was significantly changed by AAV9-d.n.FoxO during control conditions (q < 0.01) and was thus eliminated as a downstream target of FoxO in response to the C26 tumor." (PMID 25539728, 2014).
infection (1 paper, 2022). The state of being infected such as from the introduction of a foreign agent such as serum, vaccine, antigenic substance or organism. "Neurons were transfected at the time of plating with VGLUT1-pH or VGLUT2-pH and infected at DIV7 with lentiviruses expressing constructs containing either IP6K1- or IP6K3-specific shRNA hairpins, along with mTagBFP as a reporter to monitor infection efficiency." (PMID 35936490, 2022).
metabolic disease (1 paper, 2020). A congenital disorder (due to inherited enzyme abnormality) or acquired (due to failure of a metabolically important organ) disorder resulting from an abnormal metabolic process. "BBB- and BTB-impermeable IP6K1 (or IP6K1+IP6K3) selective inhibitors are desirable for the treatment of metabolic diseases." (PMID 32204420, 2020).
IP6K3 also shares sentences with these, for which no sentence is quoted: insulinoma (1 paper); lymphoma (1); Onset (1); Sepsis (1); testicular germ cell tumor (1).